TLR2 (toll like receptor 2)
Diseases named in the same sentence as TLR2 in open-access papers (continued):
Sharing a sentence is not in itself a finding about the gene and the disease.
infection (continued). "The average TLR-2 concentration assessed in unstimulated saliva of children infected with Helicobacter pylori was 4.1 pg/mL (±6.0), while in the group without infection it was much lower and amounted to 0.7 pg/mL (±0.4)." (PMID 39684489, 2024). "At 24 h post-infection, there was a powerful upstroke in the relative expression of CYP27B1 and CAMP in MAP-infected THP-1 macrophages following TLR2 siRNA transfection with an average increase of 5.55 ± 0.82 and 24.47 ± 6.41 folds, respectively (p-value < 0.01)." (PMID 38732603, 2024). "BM-MoDCs treated with IFNγ alone or IFNγ and Pam3CSK4 efficiently restricted T. gondii growth by 14 h post-infection; however, TLR2 stimulation alone was not sufficient for parasite clearance." (PMID 38538595, 2024). "Additionally, vaccine binding affinity with TLR2 and TLR3, which play a crucial role in M. tuberculosis protection following infection, demonstrated that all models elicit a good immune response." (PMID 39624097, 2024). "The average TLR2 concentration assessed in unstimulated saliva of children infected with Helicobacter pylori was 4.1 pg/mL (±6.0), while in the group without infection it was significantly lower and amounted to 0.7 pg/mL (±0.4) (p < 0.001)." (PMID 39684489, 2024). "In a study conducted in Ghana, mRNA expression of TLR2 was downregulated in whole blood of children with Sh infection compared to those without infection." (PMID 39250522, 2024). "A similar discrepancy in TLR2 expression was also observed in the lungs of DDX5+/- mice comparing to DDX5+/+ mice during 0–36 h post-infection with M. pneumoniae and during 0–24 h post-infection with S. aureus." (PMID 38182816, 2024). "There were also no noticeable differences in Rab5 and TLR-2 co-localization patterns following infection." (PMID 38675975, 2024). "Six TLRs recognize the presence of SARS-CoV-2 (TLR2, TLR3, TLR4, TLR7, TLR8, and TLR9), of which TLR2, TLR4, and TLR9 favor the pathogenicity of the virus, while TLR3, TLR7, and TLR8 favor control of the infection and resolution of the disease." (PMID 39062904, 2024). "In-vitro studies observed TLR2 mRNA expression within 48hrs of infection, while human and in-vivo studies showed TLR2 response no longer than 7 days after the infection." (PMID 39729468, 2024). "A similar increase in TLR2 and p-p65 expression was detected in primary Mettl3 cKO BMDM during 0 ~ 36 h post-infection with M. pneumoniae and during 0–24 h post-infection with S. aureus." (PMID 38182816, 2024). "Our observation that H37Rv-INH-R infection caused the highest ISG expression levels suggests a stronger induction of STAT1 as a result of cGAS-STING activation, rather than TLR2-MyD88 activation." (PMID 39597535, 2024). "In summary, TLR2 is closely related to the recognition of the gut microbiota, and whether DC expressing TLR2 plays a role in inhibiting STM infection deserves further exploration." (PMID 39080852, 2024). "As expected, LCMV-WE infection did not induce IL-6 and the effect of TLR-2 silencing in WE-infected cells was minimal if any." (PMID 38675975, 2024). "Interestingly, seven weeks post infection, this pattern shifted, as BALB/c and C57BL/6 upregulated the expression of TLR2, TLR5, TLR8, TLR9, and MyD88 mRNA." (PMID 38896633, 2024). "Higher mb-TLR2 expression was noticed in PBMCs CD8+ and CD20+ cells throughout the infection." (PMID 38140264, 2023). "Next, to investigate whether CATH-1-mediated inhibition of SS2-induced cytokine production is dependent on TLR2/4, the expression of TLR2 and TLR4 was detected through pre-incubation CATH-1 with cells 2 h prior to SS2 infection." (PMID 37605242, 2023). "Of the two S. parasuis strains, NN1 induced higher transcription levels of the TLR2 gene in primary astrocytes before 18 h post-infection and in BV2 cells at 4 h post-infection, whereas BS26 induced higher transcription levels of the TLR2 gene in BV2 cells at 8 h and 12 h post-infection." (PMID 37111486, 2023).
infection (continued). "TLR2 gene transcription patterns in the brains of BS26- and NN1-infected mice with neurological symptoms were upregulated at 48 h post-infection and peaked at 72 h post-infection." (PMID 37111486, 2023). "During infection or injury, degradation of high-molecular weight HA (HMW-HA) to low-molecular weight HA (LMW-HA) by host hyaluronidases and reactive oxygen species (ROS) is thought to stimulate proinflammatory responses mediated by TLR2 and TLR4 signaling." (PMID 37747229, 2023). "Here we report IL-27 expression by macrophages was inhibited by blocking TLR-2 and -4, and infection with M. tuberculosis strain lacking TLR ligand LpqH lipoprotein." (PMID 36863206, 2023). "The infection phenotype of the MYD88−/− mice was distinct from both the WT and TLR2−/− mice." (PMID 37404047, 2023). "In WT young mice IgG levels were increased around three times after infection, but no significant increase was visible in either aged WT or TLR2−/− mice." (PMID 37258615, 2023). "Notably, Fibronectin 1 (FN1), Toll-like receptor 2 (TLR2), and ICAM1 were involved in all three infection categories." (PMID 37233676, 2023). "Additionally, the expression of TLR2 is significantly upregulated by EV71 and UV-inactivated EV71 in the early phase of infection." (PMID 37207203, 2023). "However, in contrast to infection of the TLR2−/− and MYD88−/− macrophages, infection of p47phox−/− BMMs with the ∆tolC LVS still resulted in increased p38 phosphorylation at 30 and 60 min p.i.." (PMID 37404047, 2023). "TLR2 absence did not alter the frequency or the number of lung-infiltrating MDSCs after infection when compared to WT controls." (PMID 37524886, 2023). "Thus, the activation of TLR2 and TLR4 on other cells promotes platelet production, while the activation of TLR2 and TLR4 on platelets can regulate their functions, such as anti-infection, adhesion, and aggregation." (PMID 36674552, 2023). "Fold change with respect to infection, the level of IgG2b was significantly decreased by aging in WT mice but not in TLR2−/− mice." (PMID 37258615, 2023). "In addition, the expression levels of TLR2 and TLR9 in fish serve as indicators of its health status and its ability to defend against the viral pathogens’ infection." (PMID 38003793, 2023). "Infection with A66 resulted in TLR2-dependent TNFα release however, there was no significant impact of TLR4 on TNFα production." (PMID 36897919, 2023). "Regarding the mRNA expression, a significant increase in TGF-β1, HIF-1α, NGAL, B2M, FGF23, TLR-2, IL-18, and YKL-40 was observed in the long-term post-MHV-1 infection, whereas only NGAL was found to be significantly increased in the acute stage post-infection." (PMID 37626956, 2023). "After infection with A. hydrophila, the transcriptional levels of TLR1, TLR2, caspase 8, MyD88, FADD, TOLLIP isoform 1 and TOLLIP isoform 2 were all significantly up-regulated in the kidney, indicating that bacterial infection induced the activation of TLR signaling pathway in the yellow catfish." (PMID 37056759, 2023). "Collectively, the survival and weight loss results indicate a role for TLR2 in the early response to F. tularensis infection; however, even in the absence of TLR2, the host is able to control infection with the LVS ∆tolC mutant." (PMID 37404047, 2023). "Furthermore, we found that the human virulent Schu S4 strain similarly modulates TLR2- and MAPK-dependent signaling early during infection to dampen macrophage cell death and pro-inflammatory cytokine responses." (PMID 37404047, 2023). "While HylB promoted ascending GBS infection in wild-type (WT) and CD44-deficient mice, surprisingly, mice lacking both TLR2 and TLR4 (TLR2/4) were able to curtail these infections." (PMID 37747229, 2023). "In future research we want to focus on the role of the microbiome in control of tlr2 signaling in the presence or absence of infection." (PMID 36829598, 2023).
infection (continued). "Before infection, IgG levels were significantly elevated in healthy WT-aged mice compared to WT-young mice, whereas IgG levels did not change with age in TLR2−/− mice." (PMID 37258615, 2023). "TLR2, in conjunction with TLR1, plays an important role in the innate immune response by recognizing microbial lipoproteins and lipopeptides in the process of infection." (PMID 37056759, 2023). "Infection of murine macrophages with Porphyromonas gingivalis (Pg) induced activation of the NLRP3 inflammasome, IL-1β release, and pyroptosis via the CD36/toll-like receptor 2 (TLR2) pathway." (PMID 36544112, 2022). "On the other hand, A. actinomycetemcomitans challenge promoted a slight upregulation of TLR-2, whereas mono-infection with probiotics did not alter baseline TLR-2 mRNA levels." (PMID 35602018, 2022). "Similarly, despite the ability of TLR2 to activate phagocytic activation of macrophages due to L. donovani infection, silencing either TLR2 or TLR3 impairs the secretion of NO and TNF‐α post‐infection of IFN‐γ‐primed macrophages with L. donovani promastigotes." (PMID 35119120, 2022). "The role of TLR2 in infection outcome by L. amazonensis has not been fully understood, as the existing literature describes wide range of effects of TLR2 in L. amazonensis infection." (PMID 35119120, 2022). "While both candidates protected mice from infection following challenge, as evidenced by the reduction or elimination of RSV plaques, the inclusion of the TLR2 agonist yielded a more potent antibody response, greater protection, and a clear shift away from Th2/eosinophil responses." (PMID 36560488, 2022). "Thus, TLR2 plays a crucial role in NKT cells induced protection against Leishmania during acute and innate phase of infection." (PMID 35119120, 2022). "The expression of Toll-like receptor 2 (TLR2) and the transcription factor c-jun were induced upon PA infection in nonsmokers only." (PMID 35897707, 2022). "To identify whether S. aureus can promote osteoclastogenesis through TLR2- or TLR9-indepenent mechanisms, we next studied the response of RANKL-primed osteoclast precursors to intracellular infection with WT S. aureus." (PMID 36226943, 2022). "Our in vivo findings suggest that TLR2 and TLR9 modestly impact infection-induced bone loss and do not alter osteoclastogenesis in trabecular bone in vivo." (PMID 36226943, 2022). "At the cellular level, proteins like ICAM-1, TLR2 or Ezrin/Radixin were only up-regulated in CACs treated with the serum of asymptomatic patients at the highest peak of infection (PCR + /IgG −), but not with the serum of PCR −/IgG + individuals." (PMID 35397534, 2022). "Recent work by Zheng and colleagues provided genetic evidence that the TLR2 pathway contributes to overwhelming production of inflammatory cytokines (particularly TNF-α, IL-6 and IFN-γ) during infection by SARS-CoV-2 and other β-coronaviruses, following recognition of the E protein." (PMID 35632741, 2022). "In this study, we found that both macrophages and neutrophils moved faster in tlr2 wild type larvae than in tlr2 mutants after Mma20 infection, while tlr2 deficiency did not affect neutrophil migration in MAC 101 infection." (PMID 36741407, 2022). "Our current study did not address the role of infection-enhancing antibodies in the TLR2-mediated immune responses induced by prM-DENV." (PMID 36240261, 2022). "From these data, we conclude that TLR2 and TLR9 are partially responsible for infection-induced osteoclastogenesis in RANKL-primed cells, but TLR2- and TLR9-independent mechanisms contribute significantly to osteoclast formation during intracellular infection." (PMID 36226943, 2022). "Together, these results suggested that the activation of DCs via TLR2/MYD88 can lead to a shift in the Th1/Th2 response, frequently found in DHF patients, and might also be related to ADE events in subsequent infections." (PMID 35632732, 2022).
infection (continued). "TLR2 was shown to recognize the SARS-CoV-2 envelope E protein as its ligand and resulted in the TLR2-dependent cytokine (TNFα, GM-CSF, G-CSF, IL-6) and chemokine (CXCL10, MCP-1) release and lung damage in K18-hACE2 transgenic mice after infection with SARS-CoV-2." (PMID 35682644, 2022). "As with studies demonstrating that silencing of essential autophagy machinery does not affect mycobacterial infection outcomes in vivo, these studies do not account for the ability of Mtb to inhibit TLR2 activation by PPE51 during infection." (PMID 35467412, 2022). "On the other hand, we did not observe a further surge in TLR2 overexpression in the COPD + ICS group either after PA infection or with BUD/FLU treatment when compared with its control." (PMID 35897707, 2022). "These signaling pathways showed that, after LPS infection, several DEGs were mainly related to immune function, such as up-regulated expression of CCL5, IL8, NFKBIA, TRAF3, and TNFAIP3, and down-regulated expression of MEF2C, MAP2K6, TLR1, TLR2, and IRF5." (PMID 34067819, 2021). "A histological comparison of the brains and livers of the wild-type and TLR2−/− pups in the uninfected and infected groups showed no histological changes attributable to infection." (PMID 34675905, 2021). "In contrast, the absence of the receptor in TLR2-deficient C57BL/6 mice infected with L. amazonensis decreased parasitic load and enhanced the recruitment of inflammatory cells to the site of infection at early infection stages." (PMID 34691019, 2021). "Likewise, total and free LA levels were upregulated by Mtb or TLR2 and TLR4 stimulation, suggesting an enhanced uptake of this essential ω6 PUFA precursor by host macrophages upon infection." (PMID 34951591, 2021). "Furthermore, a previous study showed the increase in TLR2 and TNF-α as the host immune responses to the infection of B. abortus through the host immune response to pathogen infection." (PMID 33829052, 2021). "Additionally, TLR2 and TLR4 expression was higher in DL monocytes compared to CL monocytes after infection with a DL isolate (p<0.01 and p<0.05)." (PMID 34568099, 2021). "Once internalized, mycobacterial specific N-glycolyl MDP is recognized and activates NOD2, leading to synergistic interactions with TLRs and TLR heterodimers (TLR2, TLR1, and TLR6) to promote downstream activation of NF-κB signaling and a pro-inflammatory response to infection." (PMID 34485444, 2021). "Surprisingly, they discovered TLR2 activation but not TLR4 stimulation in transfected HEK293 cells during infection with B. pseudomallei LPS." (PMID 34456925, 2021). "The expression of Foxp3 was decreased in the lung of no-infection TLR2−/− mice compared with WT mice in control (p < 0.05)." (PMID 34222495, 2021). "Previously, we showed an increased expression of TLR2, TLR3, TLR5, and TLR8 in pulmonary epithelial cells at 48 h post-infection by genetically diverse M. tuberculosis clinical strains of East-Asian and Euro-American lineages, leading to production of a diverse range of inflammatory cytokines." (PMID 34502407, 2021). "TLR2−/− mice were not affected in the early stages of infection, but in the late stage of infection, the absence of TLR2 resulted in a reduction in macrophage recruitment, poor Spn clearance and, ultimately, continued inflammation in the middle ear." (PMID 34360632, 2021). "However, agonist treatment together with Δrgg3 infection resulted in decreased TNF-α production in response to lipopolysaccharide (LPS; TLR4), heat-killed Listeria monocytogenes (HKLM; TLR2), and CpG oligodeoxynucleotide (ODN1826; TLR9)." (PMID 33947757, 2021). "We demonstrate that productive infection of macrophages can be altered by TLR signaling in response to purified ligands and bacterial coinfection, with TLR2- and TLR5-mediated signaling activating HIV-1 and TLR3- and TLR4-mediated signaling repressing HIV-1 replication in MDMs." (PMID 33472928, 2021).
infection (continued). "Carriage of TLR2 + 2477*A approached significance when assessing CT positive women with a symptomatic course of infection compared to CT positive women without one (OR: 2.6, 95%CI: 0.8–8.0, p = 0.10)." (PMID 33430411, 2021). "Inactivated PPRV can also activate cells via TLR2, indicating that this activation is independent of newly synthesized viral gene products after infection." (PMID 33522421, 2021). "Some receptors, such as TLR2 and TLR9, act synergistically in helping to control the infection." (PMID 34336720, 2021). "The decreased levels of TLR2 after liver crush injury followed by infection are not limited to the PMN, since alveolar macrophages also showed decreased TLR2 expression in infected mice after liver crush when compared with infection in the absence of trauma." (PMID 34520397, 2021). "The present study endeavored to evaluate whether TLR2 and TLR4 neutralization leads to impaired monocyte infection, consequently modulating the inflammatory response observed in American tegumentary leishmaniasis (ATL) caused by L. braziliensis." (PMID 34691019, 2021). "However, greater parasite multiplication and higher TLR2 and TLR4 expression were seen in monocytes from DL patients compared to CL following infection with DL isolates." (PMID 34568099, 2021). "The log2FC of TLR2 and NLRX1 between two groups were significant (1.06 and 0.65, respectively), suggesting that gene expression changes in these genes were part of the response in the host to adapt the dosing instead of the pathological infection." (PMID 33809523, 2021). "This is substantiated by the finding that neither TLR2 nor caspase-1 KO mice displayed overt signs of morbidity and survived the infection similar to WT animals." (PMID 32290861, 2020). "On the other hand, after 24 h P. brasiliensis-A549 cell infection, we did not observe α3 integrin-TLR2 complexes." (PMID 33173103, 2020). "Therefore, the strength of TLR2 and TLR4 agonists in M1 macrophage polarization should be evaluated carefully in host resistance within each infection model." (PMID 33304649, 2020). "Higher amounts of LVS and IFN-γ gene expression were quantified in cells from TLR2 KO mice which had higher bacterial burdens, while lack of MyD88 facilitated intracellular infection but little IFN-γ production." (PMID 32745117, 2020). "Thus, TLR2 activation by RSV and ROS generation during infection will promote formation of ASC-NLRP3 inflammasome complex that activates caspase-1 for Gasdermin-D mediated pyroptosis." (PMID 32854254, 2020). "Finally, to evaluate the role of MyD88 and TLR2 in controlling LVS infection and specifically IFN-γ production by DC, TLR2 KO and MyD88 KO mice were infected with LVS, DC and neutrophils from these mice were sorted, and DNA and RNA were analyzed." (PMID 32745117, 2020). "MyD88, TLR2, TLR3, and TLR4 peak at 48, 24, 12, and 36 h after infection." (PMID 31947624, 2020). "Thus, TLR4, IL27, and TNF were activated across all groups; IFNG was exclusively activated by AMTB-127 and AMTB-205; PTGS2 was activated in AMCTs and AMTBs in response to infection with Mtb UT205, whereas TLR2 was only activated in response to Mtb UT127." (PMID 32373118, 2020). "Although we and others have previously shown that TLR-2/MyD88 signaling can influence mucosal Foxp3+ cells, Treg specific role of MyD88 was not evaluated during an infection." (PMID 33240286, 2020). "In contrast, TLR2, TLR4, and TLR9 play relatively minor roles with minimal or no impact on IFN-γ production by splenocytes, including DC, and the response of the respective KO mice to LVS infection is only modestly compromised." (PMID 32745117, 2020). "During infection with nontypeable H. influenzae, bacterial lysates induce inflammation mainly through the activation of TLR2." (PMID 33184103, 2020). "Mice lacking TLR2 survived infection for 4 days in good condition, but after this time, half of them showed signs of irreversible disease and were humanely euthanized." (PMID 32209688, 2020).